MMP14 (matrix metallopeptidase 14)
Diseases named in the same sentence as MMP14 in open-access papers (continued):
Sharing a sentence is not in itself a finding about the gene and the disease.
Ewing sarcoma (1 paper, 2019). A small round cell tumor that lacks morphologic, immunohistochemical, and electron microscopic evidence of neuroectodermal differentiation. "Another piece of evidence for MMP14 activity in Ewing sarcoma is that the same cells expressing MMP14 protein also present soluble Endoglin, a membrane coreceptor of the TGFβ family, which is cleaved by MMP14 and associates with poor prognosis in Ewing sarcoma." (PMID 31466240, 2019). "However, all cell lines used in this study expressed both MMP2 and MMP14, suggesting that MMP14 influences Ewing sarcoma cell behavior." (PMID 31466240, 2019).
Failure to thrive (1 paper, 2016). Failure to thrive (FTT) refers to a child whose physical growth is substantially below the norm. "Our findings may justify further investigation into the relationship between MMP14 and energy storage-related diseases that lead to ‘failure to thrive’ and to early death." (PMID 27478693, 2016).
gestational diabetes mellitus (1 paper, 2013). "Placental expression of MMP14 is greater in pregnancies complicated by gestational diabetes mellitus and, in vitro it is induced by insulin and IGF-II in vitro and HIF-1α." (PMID 24391823, 2013).
Gliosis (1 paper, 2023). Gliosis is the focal proliferation of glial cells in the central nervous system. "Similar to the results for mRNA levels of inflammatory markers, the peak in levels of mRNA associated with gliosis in Ins2Akita/+ mice appeared at 12 weeks of age, with increases in Tlr4 (encoding TLR4), Pcan and Mmp14 (encoding matrix metalloproteinase 14)." (PMID 37670018, 2023).
glycogen storage diseases (1 paper, 2016). "Finally, our observations on metabolic signatures, energy stores and malnutrition suggest that MMP14 may play a role in diseases with similar pathological phenotypes such as glycogen storage diseases (GSD) in addition to previously reported phenotypes." (PMID 27478693, 2016).
Hepatic steatosis (1 paper, 2024). Steatosis is a term used to denote lipid accumulation within hepatocytes. "Together with data demonstrating that trehalose and trehalose analogues attenuate diet-induced hepatic steatosis, we next sought to define the extent to which hepatocyte MMP14 deletion is sufficient to protect against hepatic lipid accumulation in vivo." (PMID 39282008, 2024).
hypospadias (1 paper, 2023). Hypospadias is the displacement of the urethral meatus on the ventrum of the penis. "Several of these MeSH terms are associated with TF (transferrin), EGF (epidermal growth factor), MMP14 (Matrix metallopeptidase 14), CDH1 (Cadherin 1), and F13A1 (Coagulation factor XIII A chain) genes, related to CLJ and hypospadias." (PMID 37238140, 2023).
intervertebral disc degeneration (1 paper, 2019). "In some studies, the association between MMP14 gene polymorphisms and other diseases, such as intervertebral disc degeneration, has also been reported." (PMID 30548828, 2019).
iron deficiency (1 paper, 2020). "The proteome profile identified 4 novel factors to be conversely regulated upon iron deficiency versus iron excess, namely CPT1A, MMP14, XDH, and PYGL." (PMID 33023155, 2020).
keratoconus (1 paper, 2014). A degenerative, structural disorder of the eye, characterized by a cone-shaped protrusion of the cornea. "MMP-2 and MT1-MMP (MMP-14) protein is expressed in multiple layers of the normal and keratoconus human CE, with MT1-MMP appearing mostly in the basal layer and MMP-2 more diffuse throughout the CE." (PMID 25412440, 2014).
kidney clear cell carcinoma (1 paper, 2019). "This leads to the upregulation of MMP14 in kidney clear cell carcinoma in patients with deletion of VHL." (PMID 31200666, 2019).
kidney tumor (1 paper, 2024). "We compared MMP-14 (membrane-type MMP 1) and MMP-15 (membrane-type MMP 2) in human kidney tumor to those in healthy parts of the same organ, which were used as a control material as ethical concerns excluded the possibility of taking a kidney sample from healthy donors." (PMID 39125675, 2024).
Leukoencephalopathy (1 paper, 2021). This term describes abnormality of the white matter of the cerebrum resulting from damage to the myelin sheaths of nerve cells. "Corroborating this, we also independently identified Mmp14 upregulation in Csf1r+/− mice, a model of leukoencephalopathy and microglial dyshomeostasis, and confirmed its capacity to degrade PNNs via in vivo injection of recombinant MMP-14 (K.N.G., unpublished data)." (PMID 34413489, 2021).
leukoplakia (1 paper, 2025). A white patch or plaque on a mucous membrane that cannot be characterized clinically or pathologically as any other disease. "Notably, leukoplakia lesions exhibited only moderate MMP-14 expression within the papillary dermis, suggesting a reduced level of extracellular matrix (ECM) remodeling relative to malignant lesions." (PMID 40572725, 2025). "In homogeneous leukoplakia, 24 cases exhibited weak cytoplasmic immunoreactivity, while three cases were completely negative for MMP-14 expression in the membranous, cytoplasmic, and nuclear compartments." (PMID 40572725, 2025).
lichen planus (1 paper, 2025). A chronic, recurrent, pruritic inflammatory disorder of unknown etiology that affects the skin and mucus membranes. "MMP-14 shows variable expression in lichen planus, and in potentially malignant lesions, this variability reflects extracellular matrix remodeling activity, essential for the initiation of malignant transformation." (PMID 40572725, 2025).
Lipedema (1 paper, 2022). Disorder of adipose tissue characterized by symmetric and bilateral enlargement of the lower extremities due to abnormal deposition of subcutaneous fat often in obese women. "An ECM/lymphatic-related signaling mechanism hypothesized for the pathophysiology of lipedema is the matrix metallopeptidase 14 (MMP14)–caveolin-1 (CAV-1) axis, wherein MMP14 and CAV-1 are mutually regulated through a feedback mechanism." (PMID 36551837, 2022). "Thus, impairment of estrogen signaling may also be a culprit in the lymphatic dysfunction in lipedema, as has been hypothesized with the MMP14–caveolin-1 (CAV-1) axis mechanism." (PMID 36551837, 2022).
malignant rhabdoid tumor (1 paper, 2022). "AFP, MSLN, MUC16, OPN, and MT1-MMP/MMP14 may serve as biomarkers for human malignant rhabdoid tumor detection and therapeutic targets." (PMID 35954348, 2022). "Membrane-type 1 matrix metalloproteinase (MT1-MMP/MMP-14) and tissue inhibitor of metalloproteinases-2 (TIMP-2) were highly expressed in these malignant rhabdoid tumor cells, indicating their invasive phenotypes." (PMID 35954348, 2022).
middle ear cholesteatoma (1 paper, 2023). "We examined the expression of MMP-14 by immunohistochemical staining 39 middle ear cholesteatoma specimens and 10 external auditory meatus epithelial cell specimens." (PMID 37904429, 2023). "In this study, immunohistochemical labeling was used to examine the expression of MMP-14 in 39 cases of middle ear cholesteatoma and 10 cases of normal external auditory canal epithelium." (PMID 37904429, 2023).
mucinous tumours (1 paper, 2021). "In a French study, serous tumours, especially the malignant ones, showed higher MMP-14 expression than the mucinous tumours." (PMID 34344453, 2021).
Oral leukoplakia (1 paper, 2025). A thickened white patch on the oral mucosa that cannot be rubbed off. "This observational study aimed to evaluate the expression patterns of Maspin, β-catenin, and MMP-14 by immunohistochemistry (IHC) in oral leukoplakia, oral lichen planus, OSCC, and normal mucosa, exploring associations with lesion type, with no prognostic inferences drawn from a single timepoint." (PMID 40572725, 2025).
oro-pharyngeal cancers (1 paper, 2017). "We have previously reported elevated levels of MMP1 and MMP14 in tissue sections from oro-pharyngeal cancer patients and also identified MMP14 as a direct p63 regulated gene in normal HFK." (PMID 26001294, 2017). "Here, we show that p63, Src, PTK2, c-Jun (activator protein-1 (AP-1) transcription factor) and MMP14 genes are upregulated in patients with oro-pharyngeal cancers." (PMID 26001294, 2017). "Up-regulation of Src, AP-1, MMP14 and p63 expression was confirmed in oro-pharyngeal cancer." (PMID 26001294, 2017).
osteonecrosis (1 paper, 2019). A none disease characterized by death of bone tissue due to a lack of blood supply. "The aim of this study was to investigate the association between polymorphisms of MMP‐14 and steroid‐induced osteonecrosis of the femoral head in the Chinese population." (PMID 30548828, 2019). "Therefore, we hypothesized that MMP14 also played an important role in the pathogenesis of steroid‐induced osteonecrosis." (PMID 30548828, 2019).
pancreatitis (1 paper, 2017). Inflammation of the pancreas. "(A) qRT-PCR for Egf, Tgfα, Hbegf, Areg, Ereg, Mmp1, Mmp2, Mmp9, Mmp12 and Mmp14 expression in littermate control, iKras* pancreata 3 weeks post pancreatitis, iKras* and iKras*;CD11b-DTR pancreata 3 days post Kras* inactivation and DT treatment." (PMID 28980940, 2017).
parathyroid disease (1 paper, 2025). "Among these, several genes such as APC, CEP152, CREBBP, FAM111A, FGFR1, KL and MMP14 have been previously suggested to be associated with parathyroid disease." (PMID 40434298, 2025). "Although classified as VUS, several candidate genes previously reported to be associated with parathyroid disease, including ITPR2, IL21R, MMP14, TWIST1 and ESR2 were identified in three patients with cancer-type tumors." (PMID 40434298, 2025).
periodontal disease (1 paper, 2025). "From the limited samples obtained, we can assume that MMP-14, and CD147 are involved in the progression of periodontal disease associated with type 2 DM and could be further investigated as potential predictive biomarkers." (PMID 40075856, 2025).
peripheral artery disease (1 paper, 2021). "We cannot exclude that the levels of MMP-14 are influenced by the presence of a potential peripheral artery disease." (PMID 34702365, 2021).
peripheral nerve injury (1 paper, 2020). Injury to a peripheral nerve. "It is reported that the extracellular domain of NG2 on macrophages is shed by their expressing matrix metalloproteinase 14 (MMP14) in peripheral nerve injury." (PMID 32967118, 2020).
pharyngeal tumour (1 paper, 2017). "Oro-pharyngeal tumour sections were also stained for Src and MMP14." (PMID 26001294, 2017).
polyneuropathy (1 paper, 2017). A disease or disorder affecting more than one nerve. "Taken together, these results suggest that MMP-14 might be a potential disease and therapeutic biomarker in TTR polyneuropathy." (PMID 28993312, 2017).
prostate (1 paper, 2020). "Analysis of peritumoral stroma, adjacent to prostate lesions spontaneously developing in HiMyc mice, revealed WAT7 binding to MMP14-expressing cells." (PMID 33317052, 2020).
pterygium (1 paper, 2025). A wedge-shaped fibrovascular lesion arising from the bulbar conjunctiva and extending to the cornea. "This small-molecule inhibitor blocks MMP-14 activity as well as collagen synthesis and migration in conjunctival fibroblasts characteristic of pterygium formation." (PMID 40565017, 2025). "In the context of pterygium pathology, the upregulation of MMP-14 and ADAM-9, -10, and -17 is observed in human pterygia." (PMID 40565017, 2025). "Among the MMP family, the elevated expression of MMP-14 in pterygium leads to the degradation of abnormally accumulated collagen, despite MMP-14’s capacity to degrade collagens type I, II, and III." (PMID 40565017, 2025). "Therefore, (R)-ND-336 is regarded as a candidate therapeutic inhibitor of MMP-14 in human pterygium." (PMID 40565017, 2025). "MMP-14 is responsible for degrading all collagen types I, II, and III that are produced in pterygium tissue, and this process supports cell migration during fibrosis." (PMID 40565017, 2025).
pulpitis (1 paper, 2019). Inflammation of the dental pulp. "The aim of the study was to evaluate MMP-14 expression in odontoblasts and in the bulk of dental pulp of teeth with pulpitis." (PMID 31486923, 2019).
rectal cancer (1 paper, 2023). A primary or metastatic malignant neoplasm that affects the rectum. "Low HDAC2 expression promotes EMT and rectal cancer metastasis by upregulating H19/MMP14." (PMID 37631010, 2023).
skin aging (1 paper, 2015). The gradual irreversible changes in structure of skin that occur as a result of the passage of time.. "Indeed, we detected a set of metallo-proteinases (MMP2, MMP14), collagens (e.g. COL6A1, COL3A1, COL5A1 and others) and elastin (ELN), which showed a significant longitudinal change in expression in addition to being closely correlated to skin aging." (PMID 25977295, 2015).
soft tissue sarcoma (1 paper, 2019). A malignant neoplasm arising from muscle tissue, adipose tissue, blood vessels, fibrous tissue, or other supportive tissues excluding the bones. "Only 1.3% of general soft tissue sarcomas present gains of the MMP14 gene." (PMID 31466240, 2019). "Interestingly, the process termed mesenchymal-to-epithelial transition (MET) has been reported in several soft tissue sarcomas, but the regulation of MMP14 during this process has not yet been described." (PMID 31466240, 2019).
steatosis (1 paper, 2021). Increased lipid within the cytoplasm of cells. "It revealed that expression levels of HSPD1 mRNA (p = 0.007), MMP14 mRNA (p = 0.015), miR-6881-5p miRNA (p = 0.046) and lncRNA lnc-SPARCL1-1:2 (p = 0.006) were independent predictors of NASH, and NAFLD scoring steatosis grading and fibrosis scoring (p = 0.04)." (PMID 34572434, 2021). "We concluded that HSPD1/MMP14/ITGB1/miR-6881-5P/Lnc-SPARCL1-1:2 panel expression has a potential in the diagnosis of NASH, and also in differentiation between NAFLD without steatosis, NAFLD with simple steatosis and NASH." (PMID 34572434, 2021). "In our study, we found upregulation in the expression of MMP14 mRNA with discriminative cutoff values between NASH cases and the healthy control group that could also discriminate between NAFLD without steatosis, NAFLD with simple steatosis and NASH." (PMID 34572434, 2021).
synovial sarcoma (1 paper, 2019). "Experimentally, MMP14 overexpression in the synovial sarcoma cell line SW982 has been shown to induce spindle shape morphology and an EMT-like phenotype, in conjunction with enhanced cell invasiveness." (PMID 31466240, 2019). "Moreover, high MMP14 expression is mainly observed in spindle cell monophasic fibrous synovial sarcomas." (PMID 31466240, 2019). "In synovial sarcoma, MMP14 protein expression is higher in TNM stages III and IV than in stages I and II, and the expression of MMP14 correlates with that of EMT-related proteins such as increased N-cadherin and decreased E-cadherin." (PMID 31466240, 2019).
systemic sclerosis (1 paper, 2025). A chronic disorder, possibly autoimmune, marked by excessive production of collagen which results in hardening and thickening of body tissues. "In systemic sclerosis, siRNA-mediated silencing of MMP14 expression in dermal fibroblasts substantially diminished TGF-β1-induced transcription of fibrotic genes." (PMID 40766297, 2025).
thoracic aortic aneurysm (1 paper, 2023). An aneurysm formed in the wall of the proximal portion of the descending aorta proceeding from the arch of the aorta. "Nevertheless, the expression trend of MMP14 in the current study is different from a previous finding in thoracic aortic aneurysms but consistent with findings in CIP-stimulated HepG2 liver cells in a Gene Expression Omnibus (GEO) dataset (GSE9166)." (PMID 36835806, 2023).
urothelial carcinoma (1 paper, 2006). A malignant neoplasm derived from the transitional epithelium of the urinary tract (urinary bladder, ureter, urethra, or renal pelvis). "In urothelial carcinoma several of the well characterised MMPs, including MMP-2, MMP-9 and MT1-MMP (MMP-14), demonstrate increased expression and activity." (PMID 16465195, 2006).
uterine sarcomas (1 paper, 2024). "Similarly, compared with other uterine sarcomas, MMP14 expression was upregulated in uLMS." (PMID 37078535, 2024).
tumor (771 papers, 1999 to 2026). "Among these, MMP-14 emerged as being particularly relevant, given its association with disease status and risk of tumor recurrence, as well as its well-documented ability to activate other MMPs, including MMP-2 and MMP-9." (PMID 40869275, 2025). "Immunohistochemistry results for MMP14-staining proved a strong upregulation of MMP14 in the tumor microenvironment, and causally validated the targeted action of the theranostic NPs, Ferumoxytol-FITC-VDA, towards GBM, with its MMP14-cleavable VDA." (PMID 40135284, 2025). "ATC-CAFs showed high expression levels of genes associated with tumor invasion (MMP14, LOXL2, and PGK1)." (PMID 38478516, 2024). "The designed linker was susceptible to cleavage by tumor-specific matrix metalloproteinase-14 (MMP-14)." (PMID 39543114, 2024). "Compared with MM and LM, uLMS tumours showed increased expression of four of six genes encoding collagen‐degrading MMPs, including MMP14 as the most highly expressed MMP in uLMS." (PMID 37078535, 2024). "Higher expression levels of MMP-2, MMP-9, and MMP-14 were associated with advanced tumor stage, lymph node metastasis, and poorer prognosis." (PMID 38089632, 2023). "MMP14 expression in CAFs and the tumour nest at the TSI were significantly associated with pENE + and TME features, such as TB, pLN+, pN2/3, lymphatic invasion (Ly), and perineural invasion (Pn) (p < 0.05)." (PMID 36765296, 2023). "Immunohistochemical analyses of total MMP14 expression in the tumour nest and cancer-associated fibroblasts (CAFs) were performed using the MMP14 co-scoring system (high- or low-risk)." (PMID 36765296, 2023). "High-risk cases according to the MMP14 co-scoring system, including the total MMP14 enzymatic activity derived from tumour nest and CAFs, were associated with ENE+; 83% of them had ENE+ (p < 0.05)." (PMID 36765296, 2023). "MMP14 expression increased the average speed of γδ T cells in the ECM to the speed exhibited in the tumor tissue, supporting the functional role of MMP14 in cleaving the tumor-associated ECM (right)." (PMID 37139603, 2023). "MMP14 expression in tumour nest and the MMP14 co-scoring system were also associated with DR (p < 0.05)." (PMID 36765296, 2023). "This study indicated that MMP14 expression in metastatic LNs is associated with ENE + and that MMP14 levels in tumours and CAFs at the TSI are highly concordant with the ENE sites." (PMID 36765296, 2023). "Analysis of gene expression data revealed that high MMP14 expression was associated with tumor progression and implicated both cancer-associated fibroblasts (CAFs) and tumor-associated macrophages in such progression." (PMID 36052235, 2022). "Parallel studies showcase the abundance of tumor-secreted factors, such as matrix metalloproteinase-14 (MMP-14), capable of causing SNHL through spiral ganglion neuron fiber and synapse damage." (PMID 35372070, 2022). "Particularly, MMP-2, MMP-7, MMP-9, and MMP-14 have been associated with tumor invasion and metastasis by their capacity to degrade the ECM." (PMID 34638415, 2021). "Particularly, MMP2, secreted by activated fibroblasts, turns on the membrane-associated MMP14 (also called MT1-MMP) at the filopodia level of tumor cells, degrading the basement membrane and inducing cell extravasation." (PMID 34503252, 2021). "MMP14 expression is highly associated with the prognosis of a variety of cancers and tumor immune invasion and has important effects on pan oncologic MMR, MSI, TMB, DNA methylation, and immune checkpoint genes." (PMID 34604053, 2021). "MMP14 is a matrix metalloproteinase that targets components of the extracellular matrix and is tightly associated with tumor progression and cell migration." (PMID 32344433, 2020). "We measured the level of MMP-14 in tumor secretions from primary VS cultures using enzyme-linked immunosorbent assay (ELISA)." (PMID 32848608, 2020).